SDHD (succinate dehydrogenase complex subunit D)
Diseases named in the same sentence as SDHD in open-access papers (continued):
Sharing a sentence is not in itself a finding about the gene and the disease.
malaria (1 paper, 2020). Malaria is a serious and sometimes fatal disease caused by a parasite that commonly infects a certain type of mosquito which feeds on humans. "All human proteins in this cluster were known to be drug targets and there were 19 associations of these five human proteins (SUCLG1, SDHA, SDHB, SDHC, and SDHD) and five malaria proteins (PVX_096130, PVX_123265, PVX_003675, PVX_113540, and PVX_003575)." (PMID 32075230, 2020).
mitochondrial complex II deficiency (1 paper, 2021). "Here we describe four Palestinian siblings presenting in childhood with clinical features indicative of mitochondrial disease and a likely pathogenic homozygous SDHD variant, consolidating SDHD gene variants as a likely cause of autosomal recessive mitochondrial complex II deficiency." (PMID 34012134, 2021).
Mitochondrial encephalopathy (1 paper, 2012). "Recently, a mitochondrial encephalopathy was reported to be caused by SDHD mutations." (PMID 22995659, 2012).
nephropathic cystinosis (1 paper, 2006). An autosomal recessive condition caused by mutation(s) in the CTNS gene, encoding cystinosin. "For example, SIV-infected genome contains upregulated aldehyde dehydrogenase 5 family member A1 (ALDH5A1, ID: H06676); and concurrent down regulated succinate dehydrogenase complex, subunit D (SDHD, ID: AA035384) and nephropathic cystinosis (CTNS, ID: W94331)." (PMID 16956415, 2006).
neurofibromatosis syndrome (1 paper, 2022). "Two nonsyndromic patients (cases 1 and 2) were negative to germline mutations in genes VHL, SDHB, SDHC, SDHD, SDHAF2, TMEM127, and MAX, while the third case (case 3) had clinical diagnosis of neurofibromatosis syndrome." (PMID 36187102, 2022).
oral cancer (1 paper, 2020). "Although in this experiment we did not detect significantly altered expressions of NDUFA10 and SDHD, their significant synergism in PTC may explain why they are both up-regulated in oral cancer." (PMID 32887258, 2020).
papillary thyroid carcinoma (1 paper, 2015). "To further determine if SDHDv affects PTEN function in papillary thyroid cancer cell line, we next transfected 8505C cells with SDHD wild-type, SDHD-G12S and SDHD-H50R plasmids, respectively." (PMID 25149476, 2015).
Parkinson disease (1 paper, 2020). A progressive degenerative disorder of the central nervous system characterized by loss of dopamine producing neurons in the substantia nigra and the presence of Lewy bodies in the substantia nigra and locus coeruleus. "In general, levodopa inhibited the growth of ESCC cells through regulating pathways involved in oxidative phosphorylation, NAFLD, and Parkinson disease, down-regulating the levels of SDHD, NDUFS4, and MT-CO3, and inhibiting oxidative phosphorylation." (PMID 33101026, 2020).
Stroke (1 paper, 2023). Sudden impairment of blood flow to a part of the brain due to occlusion or rupture of an artery to the brain. "The results showed that SDHD was substantially upregulated in the stroke group, while the same trend was seen in expression of FERMT3." (PMID 36968495, 2023). "In the current study, LASSO regression analysis and random forest algorithms found two signature genes, then three validation datasets, including GSE140275, GSE122709, and GSE180470, confirmed that SDHD and FERMT3 were highly expressed in the stroke group." (PMID 36968495, 2023). "In conclusion, we identified two signature genes (SDHD and FERMT3) in peripheral blood of stroke patients by machine learning." (PMID 36968495, 2023). "SDHD and FERMT3 were highly expressed in the stroke group, suggesting that these genes may play a significant role in stroke." (PMID 36968495, 2023). "Nonetheless, correlations of FERMT3 and SDHD with stroke have not been previously reported." (PMID 36968495, 2023).
testicular seminoma (1 paper, 2019). A malignant germ cell tumor arising from the testis. "A distinctive case of testicular seminoma has been reported in a carrier of germline SDHD mutations, which presented the loss of the wild type allele in tumor cells." (PMID 31372201, 2019).
thyroid nodule (1 paper, 2024). A small circumscribed mass in the THYROID GLAND that can be of neoplastic growth or non-neoplastic abnormality. "Here we report a case of a TPGL presenting as an indeterminate thyroid nodule (TN) ultimately leading to the diagnosis of multifocal head and neck PGL syndrome due to a pathogenic variant in succinate dehydrogenase complex subunit D (SDHD)." (PMID 39156002, 2024). "Evaluation of an incidentally discovered indeterminate thyroid nodule (TN) in a previously healthy 59-year female led to diagnosis of thyroid paraganglioma (TPGL) and subsequently hereditary succinate dehydrogenase complex subunit D (SDHD)-related multifocal head and neck paragangliomas (PGLs)." (PMID 39156002, 2024).
uveal melanoma (1 paper, 2015). A melanoma derived from melanocytes of the uveal tract. "Based on lack of detected SDHD promoter mutations (addressed below), the 51 primary uveal melanoma samples were excluded from further statistical analyses." (PMID 26327518, 2015).
uveal tumor (1 paper, 2015). "None of the 51 uveal tumor samples analyzed harbored a SDHD promoter mutation." (PMID 26327518, 2015).
tumor (102 papers, 2004 to 2026). "Paternal inheritance was included in the evaluation of variants in the SDHD gene, as only paternally inherited PVs in SDHD are known to be associated with a high risk of developing a component tumor." (PMID 38473309, 2024). "We subjected the FFPE tumor tissues obtained from patients harboring the SDHD:pH102R variant to IHC analysis of the expression pattern of the SDHB subunit." (PMID 36614070, 2022). "Worth noting is that one out of five patients with a pathogenic SDHD variant presented with multifocal disease, and in one out of five patients tumor invasion into the VCI was documented." (PMID 35784570, 2022). "Of the 35 tumours analysed for genetic variants, 25 carried variants in SDHD, 7 in SDHB and 1 in SDHC." (PMID 36178902, 2022). "Given the young age, tumour histotype and the presence of cytoplasmic vacuoles, the possibility that the SDHD variant resulted in the tumour was considered." (PMID 35938916, 2022). "The maternal transmission of this gene explains the need for the loss of the entire maternal chromosome 11 for tumor formation and the low frequency of maternal inheritance of the SDHD mutations." (PMID 36614070, 2022). "People with SDHD mutations have the highest penetrance, with multiple tumours most frequently located in the head and neck region (parasympathetic), whereas SDHB mutations predispose carriers primarily to retroperitoneal PPGL (sympathetic)." (PMID 34021277, 2021). "The majority of probands with SDHD variants presented with HNPGL or HNPGL combined multifocal tumours (25/27 patients, 92.6%)." (PMID 34439168, 2021). "The tumor recurred 22 years later as a cerebellar metastasis and both tumors were found to carry the same SDHD mutation suggesting an inherited origin." (PMID 32926213, 2020). "In a case series of 4 patients, two of them with SDHD mutation, octreotide treatment was able to stabilize tumor size in one patient with SDHD mutation (50%)." (PMID 32098148, 2020). "Negative or weak diffuse SDHB staining was found in nine out of ten cases with pathogenic/likely pathogenic SDHD variants; one SDHD-mutated tumor showed positive staining of all SDH subunits." (PMID 32971818, 2020). "The corresponding germline DNA from PCC6 showed the variant to be present in a heterozygous fashion, indicating loss of the wild type SDHD allele in the tumor DNA." (PMID 31052272, 2019). "Significantly higher COX-2 mRNA levels in head and neck PPGLs compared to other tumor locations is related to the fact that all head and neck PPGLs in this series carried an SDHD mutation." (PMID 31142060, 2019). "The SDH complex consists of four subunits (SDHA, SDHB, SDHC, and SDHD), and a deficiency of this enzyme is known to activate tumor formation through dysregulation of HIF activity." (PMID 31817761, 2019). "The model proposes that maternal chromosomal 11 loss results in the simultaneous deletion of the SDHD wild type gene and an as yet unidentified exclusively maternally expressed gene (or genes), resulting in tumor formation." (PMID 28099933, 2017). "Of the SDH mutations, SDHD-related tumours are commonly seen in the head and neck region and are usually multiple." (PMID 29166454, 2017). "SDHD (11q23.1) is a well-known tumour-suppressor gene frequently mutated in familial paraganglioma and pheochromocytoma." (PMID 28662712, 2017). "Mutations in SDHD gene has been initially reported to be associated with hereditary paraganglioma and SDHD has been suggested to play a role as tumor suppressor." (PMID 25894340, 2015). "Mutations in SDHD and other SDHx genes have been implicated not only in primary metabolic dysfunction, but also as drivers of neoplastic transformation in various tumour types." (PMID 26008905, 2015). "A previous biological analysis in the tumor tissue from a PGL patient harboring a loss-of-function SDHD germline mutation (R22X) showed that SDH activity was abolished due to the mutation and associated with increased expression of HIF-1α." (PMID 25149476, 2015).
tumor (continued). "Microsatellite analysis in the tumor of patient 1 provided evidence for somatic recombination and loss of the paternal region of chromosome 11 including SDHD and the maternal chromosome including the centromere and the p arm." (PMID 25300370, 2014). "In patients, tumor formation in heterozygous, paternally inherited SDHD-mutation carriers requires the loss of the maternal allele in a phenomenon known as loss of heterozygosity." (PMID 24465590, 2014). "As for SDHD related tumors, tumor formation in FH heterozygotes is associated with loss of the second allele." (PMID 25126540, 2014). "Germline mutations of the SDHD gene show a ‘parent-of-origin’ expression phenotype, with tumor development occurring only when mutations are inherited via the paternal line." (PMID 25300370, 2014). "Tumours associated with SDHD mutation are rarely malignant, in contrast to those arisen from mutation of the SDHB gene." (PMID 19243216, 2009). "Denaturing high performance liquid chromatography (DHPLC) analysis and subsequent sequencing of the SDHD gene in 31 NB cell lines and 67 NB tumour samples revealed the presence of sequence variants in 5 NB cell lines and 4 NB tumour samples." (PMID 15331017, 2004). "Whereas individuals with paternally‐inherited SDHD PVs have an SDH‐related tumor risk over 40%, the risk for SDH‐related tumors in someone with an SDHA PV may be as low as 1.7%." (PMID 39927693, 2025). "We examined the loss of various regions on chromosome 11, including the SDHD gene locus and the 11p15.5 region, which is thought to contain the imprinted second tumor suppressor gene (TSG) involved in tumor formation, explaining the phenomenon of paternal transmission of SDHD-mutated PPGLs." (PMID 36614070, 2022). "Additionally, paternally transmitted mutations with somatic loss of the normal maternal SDHD region is shown in affected individuals, suggesting SDHD as a tumor suppressor gene that requires both alleles to be inactivated following Knudson’s two-hit model." (PMID 36614070, 2022). "More rarely, SDHD mutation carriers can develop other kinds of tumor." (PMID 32098148, 2020). "Germline DNA was only available for PCC6 and showed the SDHD variant in a heterozygous fashion, indicating loss of the wild type (WT) SDHD allele in the tumor, which was also confirmed by the loss of heterozygosity analyses for microsatellite markers flanking the SDHD gene." (PMID 31052272, 2019). "Interestingly, in family 4, the distribution of individuals with tumors was compatible with maternal transmission, differing from prior reports of tumor development occurring predominantly through paternally inherited SDHD mutations." (PMID 31365623, 2019). "The tumor ID69 with a pathogenic SDHD variant additionally harbored a somatic missense variant of unknown significance in FH (p.(Ala198Val)) with a low allele frequency (7.3%), indicating a potential secondary event." (PMID 31212687, 2019). "Also, SDHD mutation has a distinctive phenotype and recognized increased age-related tumor risks with extremely destabilizing SDHB missense mutations." (PMID 31372201, 2019). "In addition to tumour type susceptibility differences for individual genes, we confirmed that the SDHD:p.Pro81Leu mutation has a distinct phenotype and identified increased age-related tumour risks with highly destabilising SDHB missense mutations." (PMID 29386252, 2018). "Tumours associated with SDH mutations (of which SDHD mutations are more frequent in adrenal phaeochromocytoma) tend to be associated with elevated methoxytyramine and also normetanephrine; NF1 and MEN2 with elevated metanephrine and VHL with elevated normetanephrines." (PMID 28965289, 2017). "Somatic, tumor-specific SDHD mutations have also been shown in SI-NETs." (PMID 28634180, 2017). "In the 92 tumor exomes with sufficient coverage we detected 4 SDHD promoter variants (4.3%)." (PMID 26327518, 2015).
tumor (continued). "In light of the results obtained, we hypothesized that a check-point mechanism is activated upon total SdhD loss, which must be overcome by a subsequent third hit in order for the tumor transformation to occur." (PMID 24465590, 2014). "Tumours from HPGL patients with SDHD mutations revealed enhanced expression of HIF as well as VEGF." (PMID 17211469, 2007). "The presence of the IVS3-29A>G, S68S and IVS4-32T>C variants in a cell line (NGP) and two tumours (F18 and F35), in which one of both SDHD alleles has been deleted, indicates that all three variants are located on the same allele, representing a low frequent haplotype." (PMID 15331017, 2004). "This region harbours SDHD, which encodes the small subunit D (cybS, cytochrome b558) of the mitochondrial respiratory chain complex II (succinate-ubiquinone oxidoreductase) and was recently recognized as a prototype tumour suppressor gene." (PMID 15331017, 2004). "Although there was no germline DNA available for PCC46, the homozygous expression of the SDHD p.Lys122Arg variant in the tumor could be explained by the potential loss of the SDHD wild type, since the SNP array results showed loss of chromosome 5, which includes the SDHD gene." (PMID 31052272, 2019). "Indeed, SDHD was the first tumor-suppressor gene identified as encoding a mitochondrial protein." (PMID 25126540, 2014). "Moreover, as the LOH in PGL1 implicates the loss of the entire chromosome, it could also be possible that other loci needed to prevent the tumor are still present upon deletion of the SdhD in our model." (PMID 25126540, 2014). "All four succinate dehydrogenase subunits were significantly upregulated in tumor tissues when compared to controls and showed an alignment with the TCGA except SDHD, which was significantly downregulated in TCGA." (PMID 41751859, 2026). "Pathogenic variants of SDHD and SDHAF2 confer a remarkable parent-of-origin tumour risk, in which paternally inherited variants cause tumours but maternally inherited variants do not." (PMID 41915642, 2026). "Germline testing is recommended for SDHA, SDHB, SDHC, and SDHD across all ages and tumor types in the setting of SDH‐deficient staining and/or when an SDHx PV is identified in the tumor." (PMID 39927693, 2025). "Assessing these differences for each individual gene in association with tumor location shows that proportionally more HNPs were reported for European patients with PVs in SDHA, SDHB, SDHC, and SDHD than for Asian patients." (PMID 38481600, 2024). "Accordingly, we observed up-regulation of the Succinate dehydrogenase complex, a tetramer consisting of SDHA, SDHB, SDHC and SDHD subunits that exerts a critical tumor suppressive role and has been proposed as an important therapeutic target in HCC." (PMID 36203462, 2022). "A transcriptomic analysis of 76 inherited and sporadic PPGLs identified 2 tumour clusters, one including SDHB, SDHD and VHL-mutated tumours (pseudohypoxic signalling cluster), and one comprising RET and NF1-mutated (kinase signalling cluster) tumours." (PMID 35938916, 2022). "Multifocal tumours, which were present in two patients in this study, are typical for SDHD‐positive patients and are normally seen in 79% of SDHD‐positive patients." (PMID 33851515, 2021). "Consistently, suppression of SDHD was observed in chemoresistant tumor tissues obtained from patients." (PMID 34763667, 2021). "In SDHB-related syndrome, PPGL maintenance seems to be reduced compared to SDHD (p = 0.04 vs 0.95) due to higher probability of tumor cell regression in SDHB vs SDHD (p = 0.87 vs 0.00)." (PMID 30106970, 2018). "SDHD was expressed also in adjacent non-tumour eye structures, mostly iris, retina and ciliary pigment epitheliums." (PMID 28662141, 2017).